IL6 (interleukin 6)
Diseases named in the same sentence as IL6 in open-access papers (continued):
Sharing a sentence is not in itself a finding about the gene and the disease.
COVID-19 (continued). "In particular, IL-6 is the key cytokine underlying the cytokine release syndrome, a systemic inflammatory response triggered by various factors including viral infections such as severe influenza and COVID-19." (PMID 36121891, 2022). "Interestingly, COVID-19 patients showed a down-regulation of this anti-neuroinflammatory miRNA, which in turn causes an increase in expression of IL-6, IL-8, IL-17, and other inflammatory cytokines." (PMID 36268187, 2022). "In the current study, if insulin is properly adjusted and its action boosted, its association with IL-6 may turn out to be a beneficial routine for critically ill and diabetic COVID-19 patients." (PMID 35530861, 2022). "In addition, correlation analysis results revealed that cycle threshold values of SARS-CoV-2 Omicron variant ORF1ab and N were negatively correlated with IL-6 and IL-8 levels and positively correlated with eosinophil count in patients with COVID-19." (PMID 36620263, 2022). "The US diet contains large amounts of n-6 fatty acids (including arachidonic acid, which is converted into leukotrienes, and thromboxanes) and increased cytokines, such as interleukin (IL)-1, IL-6, and tumor necrosis factor, which are risk factors for COVID-19." (PMID 35276992, 2022). "The mechanism behind the development of lymphopenia in COVID-19 is suggested to be multi-factorial: direct cell infection by the virus, indirect destruction by hyper-inflammation caused via IL-6 and TNF-α pathways, and lymphocytes recruitment to the inflammatory lung tissues." (PMID 36453635, 2022). "Increased IL-6 level is associated with COVID-19 severity and poor prognosis." (PMID 35369061, 2022). "Taken together, these results showed that IL-6 and IL-8 were associated with the disease severity of COVID-19 patients, which may be used to predict patients' prognoses." (PMID 35540724, 2022). "Patients with COVID-19 have increased Th1 and Th2 response two weeks after the onset of infection, and present with extended lung damage and risk of death when elevated levels of Interleukin-6 (IL-6) are detected." (PMID 34542252, 2022). "Higher IL-6 levels have also been linked to increased COVID-19 mortality." (PMID 36299504, 2022). "IL-6 is now available on several automated diagnostic platforms and can be easily analyzed even in an emergency and the targeted reduction of its activity by Tocilizumab has been demonstrated a good opportunity in COVID-19 patients." (PMID 35563218, 2022). "Moreover, elevated levels of IL-6 have been associated with the severity of COVID-19, implying an ‘added push’ toward lung damage; thus it has been considered as a biomarker of COVID-19 severity." (PMID 36415655, 2022). "Sera biomarkers that indicate cardiac damage, inflammation and thrombosis such as troponin T and I, CRP, tumor necrosis factor (TNF), IL-1β and IL-6 have been found to be associated with increased mortality as well as being elevated in males with COVID-19 compared to females." (PMID 36292038, 2022). "The significantly increased levels of the most relevant cytokines modulating the inflammatory processes, such as IL-6 and IL-10, further support the notion that increased systemic inflammatory conditions are associated with poorer COVID-19 outcomes, especially in the setting of geriatric patients." (PMID 36522763, 2022). "In conclusion, despite a relatively limited sample size in the acute phase of SARS-CoV-2 infection, our results indicate that individuals with prediabetes faced an increased risk of developing severe COVID-19, which correlated with high serum levels of IL-6 in these patients." (PMID 35898449, 2022). "However, in COVID-19, cytokines present, such as IL-6, can cause T lymphocyte reduction and dysfunction." (PMID 36532727, 2022).
COVID-19 (continued). "As regards abnormal host response, several studies have reported that the death of COVID-19 patients is caused by an extreme release of circulating cytokines such as IL-1, IL-2, IL-6, IL-10, TNF-α, and IFN-γ from their immune system, a condition termed the cytokine storm." (PMID 36359290, 2022). "High levels of IL-6 were associated with reduced survival in patients with COVID-19." (PMID 35746659, 2022). "We have also found that male COVID-19 patients with a higher risk of progression to a severe-critical disease present higher levels of inflammatory markers (serum IL-6, blood neutrophil counts) and tissue damage (LDH), and more marked lymphopenia, as compared to age-matched female patients." (PMID 35351135, 2022). "Moreover, an increase in interleukin (IL)-6 among COVID-19 patients also causes an increase in free iron by elevating ferritin levels, and acidosis increases free iron by reducing the ability of transferrin to chelate iron." (PMID 36045713, 2022). "In our study, IL-6 levels were associated with the severe form of acute COVID-19." (PMID 35846757, 2022). "Later, it was demonstrated that the treatment of leronlimab antibody (CCR-5 blocker) restores the levels of CD4+ and CD8+ T cells, reduces plasmatic IL-6, and decreases the SARS-CoV-2 viremia." (PMID 35062298, 2022). "Furthermore, later studies showed that, among critical ill COVID-19 patients the use of tocilizumab—a humanized monoclonal antibody against interleukin-6—is associated with lower in-hospital mortality." (PMID 36319681, 2022). "This makes pathophysiologic sense in acute COVID-19, as male sex at birth is linked to elevated basal levels of those proinflammatory cytokines (IL-6, CRP), coagulation factors, and complement components implicated in the hypercoagulable and proinflammatory state of acute SARS-CoV-2 infection." (PMID 35912863, 2022). "A lower lymphocyte count may indicate an association with COVID-19, a process that is probably controlled by the initiation of homing factors and widespread apoptosis/cell death by IL-6 and Fas-FasL interactions." (PMID 36471327, 2022). "An example might be COVID-19-associated hyperferritinemia associated with increased IL-6, in which ferritin and IL-6 may serve as biomarkers of ferroptosis: ferroptosis inhibitors may have a therapeutic role in that setting." (PMID 35360192, 2022). "It was found in the present study that elevated IL-6 levels were significantly associated with an increased risk of poor outcomes (205.50±675.47 in deceased versus 117.37±279.23 in discharged; p<0.05) among COVID-19 patients." (PMID 36277580, 2022). "Disturbance of IL-6 production is associated with the onset, progression and severity of respiratory, cardiovascular, and digestive manifestations and even mortality in patients with COVID-19." (PMID 35887067, 2022). "Cytokine dysregulation (particularly transforming growth factor-β (TGF-β), Tumor Necrosis Factor (TNF)-α, Interleukin (IL)-1β, Interferon (IFN)-γ, IL-6, and IL-10) are known to be associated with psychiatric disorders, and have been shown to be elevated in patients with COVID-19." (PMID 35053059, 2022). "Interestingly, we noted that cytokines widely associated with COVID-19 severity such IL6, CXCL10, and TNF showed multiple but modest correlations with clinical parameters in all groups, likely reflecting their multifunctional role in disease development." (PMID 34957382, 2022). "Likewise, lactate dehydrogenase and IL-6 are known risk factors for cardiac and thrombotic events in COVID-19 infection." (PMID 36171201, 2022). "Based on our finding, allele G plays a positive role against COVID-19 by reducing IL-6, which is consistent with the function of GPNMB in that it weakens the immune response against cancer cells and infections, contributing to cancer development or chronic infections." (PMID 35368020, 2022).
COVID-19 (continued). "In addition, epigenetic changes in the ACE2 receptor and in cytokine genes, such as IL-6, are also associated with severe COVID-19." (PMID 35062298, 2022). "In conclusion, we found that serum levels of IL-6, IL-8, and IL-10 were associated with the disease severity of COVID-19 patients, and serum levels of IL-1β, IL-6, and IL-8 were associated with the prognosis of COVID-19 patients." (PMID 35540724, 2022). "Furthermore, higher IL-6 has been shown to be associated with severity and higher mortality rate in COVID-19." (PMID 35500008, 2022). "According to clinical studies, an abnormal concentration of various cytokines (such as TNF-α, IL-6, IL-8) and an excessive release of reactive oxygen species in COVID-19 could cause an overactive immune response in COVID-19." (PMID 36210820, 2022). "Furthermore, severe COVID-19 is associated with excessive release of pro-inflammatory cytokines, such as IL-1, IL-6, IFN-γ, and TNF-α, which were shown to decrease the synthesis and secretion of apolipoproteins in hepatic cell lines in a dose-dependent manner." (PMID 35402531, 2022). "Moreover, a recent meta-analysis including 27 randomized clinical trials has shown that the administration of IL-6 antagonists is associated with reduced 28-day all-cause mortality of critically ill patients with COVID-19." (PMID 36182930, 2022). "Consequently, patients with levels of IL-6 signalling variables above cut-offs presented a significant increased risk of developing severe COVID-19 (IL-6: OR 12.59 (5.66 - 28.0); sIL-6R: OR 8.19 (3.60 - 18.61); sgp130: OR 7.69 (3.69 - 16.01))." (PMID 35634332, 2022). "Based on these data, a randomized phase II, placebo-controlled study assessed the efficacy of BLD-2660 in hospitalized COVID-19 subjects, assuming its ability to downregulate IL-6 and reduce potential long-term fibrosis and loss of pulmonary function resulting from SARS-CoV pneumonia (NCT04334460)." (PMID 36359334, 2022). "IL-6 is a crucial main factor in cytokine storm and has been reported to be present at high levels in severe COVID-19 patients, which may cause severe damage to lung tissue." (PMID 35287350, 2022). "Baricitinib also caused a significant reduction in plasma IL-6 in rheumatoid arthritis patients, these observations together indicating the potential of this drug to inhibit the hyperinflammation associated with COVID-19." (PMID 35746559, 2022). "Additionally, the pathogenesis of COVID-19 is associated with elevated cytokines such as IL-1β, IL-6, and TNF-α." (PMID 36160713, 2022). "Therefore, receiving a COVID-19 vaccine shortly after COVID-19 infection is likely to cause more pronounced inflammation and autoimmunity due to IL-6 overproduction." (PMID 35746474, 2022). "The COVID-19 pathophysiology characterized by release of inflammatory cytokinessuch as IL-1 and IL-6 could explained this risk as a true immunothrombosisphenomenon." (PMID 39077187, 2022). "IL-6 is a key cytokine involved in the cytokine storm, i.e. a hallmark of severe COVID-19." (PMID 35757770, 2022). "Thus, immune-inflammatory indicators, especially CD3+CD4+ T cells and IL-6, are recommended to distinguish the people who refer to a high risk of cardiac injury and mortality from COVID-19 patients with DM." (PMID 36123740, 2022). "In patients with COVID-19, IL-6 levels were linked to death in a large retrospective cohort study." (PMID 36506506, 2022). "In this cross-sectional analysis of a prospective COVID-19 recovery cohort, we found that higher antibody levels, markers of inflammation (hsCRP and possibly IL-6), and possibly pericardial effusions were associated with cardiopulmonary PASC at a median of 7 months after infection with SARS-CoV-2." (PMID 35389890, 2022). "However, steroids and IL-6 or its receptor inhibitors can cause immunosuppression in patients with COVID-19, and therefore contribute to the suppression of antiviral immunity and lead to secondary bacterial and fungal infections." (PMID 36325402, 2022).
COVID-19 (continued). "PDM seems to be associated with increased risk of severe COVID-19, as well as higher serum levels of IL-6, which may constitute a potential biomarker of severe COVID-19 risk in affected patients." (PMID 35898449, 2022). "Severe COVID-19 patients receiving anti- IL-6 therapy may be at risk for developing pulmonary fibrosis." (PMID 35371880, 2022). "In COVID-19 patients, elevated levels of the inflammatory cytokine IL-6 were linked to a higher risk of death in retrospective studies, suggesting that it may operate as a crucial mediator for respiratory failure and shock." (PMID 35632654, 2022). "Among them, IL-6 is a pleiotropic cytokine that is a major player in chronic inflammation (which is closely associated with chronic inflammatory diseases, autoimmune diseases, and cancer) and cytokine storm (such as the cytokine storm of COVID-19)." (PMID 36483254, 2022). "Patients with more severe forms of COVID-19 might be at high risk, as it was demonstrated that elevated levels of IL-6 and high IL-1β levels are correlated with a poor prognosis in the setting of ACS." (PMID 35888173, 2022). "Therefore, the aim of this study was to analyze the association between IL-6 and hematological and inflammatory parameters with outcomes of patients with COVID-19 in Kosovo." (PMID 35873360, 2022). "Elevated IL-6 levels, in particular, is strongly associated with worse survival with COVID-19." (PMID 35259186, 2022). "Therefore, exacerbated inflammatory responses within 24 h of admission correlate with COVID-19 severity in diabetic individuals, in particular IL-6 and LDH, whose longitudinal analyses hold an association with worse outcomes." (PMID 35957939, 2022). "Excessive suppression of Th1 and IFN-γ production is related, on the other hand, to an inadequate rise in the i2-response in severe cases of COVID-19, and additional causes of IL-6 and IL-10 overproduction may be detected." (PMID 35163638, 2022). "Moreover, high levels of IL-6 are associated with the higher mortality rate in ICU- (intensive care unit-) treated COVID-19 patients." (PMID 35281470, 2022). "Associations between IL-6 production and COVID-19 severity have been widely reported." (PMID 35898449, 2022). "CRP and IL-6 are also elevated in COVID-19 and are associated with worse prognosis." (PMID 38566903, 2022). "Interleukin IL-6 is a hallmark of the cytokine storm observed in severe COVID-19 patients." (PMID 36362378, 2022). "Taken together, levels of IL-6, IL-8, and IL-10 were associated with the disease severity of COVID-19, and levels of IL-1β, IL-6, and IL-8 were correlated with the prognosis of COVID-19 patients, which may be used to predict the disease severity of COVID-19." (PMID 35540724, 2022). "For example, RA patients who are under high dose of immunesuppressants at time of COVID-19 hospitalization would have a higher risk than benefit if administered IL-6, JAK or IL-1 inhibitor as this drugs will increase the possibility of serious hospital-acquired infections." (PMID 36295089, 2022). "In one of the largest, multicentre studies to date, the use of anti-IL6 treatments was associated with increased of IFD in the COVID-19 cohort (OR: 2.93, P: 0.0017), and the dual use of dexamethasone and anti-IL6 treatments were significantly associated with CAPA (OR: 2.7, P:0.027)." (PMID 36531987, 2022). "Therefore, much interest exists in controlling the overproduction of IL-6 caused by aberrant immune activation in some patients with severe COVID-19." (PMID 35343397, 2022). "Thus IL-6 and GM-CSF are also considered markers of poor prognosis in the later stages of COVID-19, and these proinflammatory mediators can predispose patients to respiratory failure and eventually ARDS." (PMID 35464491, 2022). "Severe influenza is also associated with elevated IL-6, at concentrations equivalent to COVID-19." (PMID 35531376, 2022).
COVID-19 (continued). "Prolonged mechanical ventilation, immunosuppressive treatments (i.e., corticosteroids and/or IL-6 signaling blockade) and immune dysfunctions observed in severe COVID-19 patients might be responsible for their higher risk of nosocomial infections." (PMID 36053369, 2022). "As COVID-19 is associated with hypercytokinaemia, cytokines, like IL-1, IL-6 and TNFα, may induce cell death." (PMID 36514048, 2022). "Also, a recent meta-analysis involving nine studies showed that mean serum level of IL-6 was more than three-fold higher in complicated COVID-19 cases, and was also associated with in-hospital mortality risk." (PMID 35222429, 2022). "However, the treatment with IL-6 antagonistfailed in demonstrating a lower risk of VTE events in COVID-19 patients, but apotential confounding factor appears when administered simultaneously withstandard prophylactic anticoagulation." (PMID 39077187, 2022). "Moreover, another retrospective analysis on a subset of a large cohort of COVID-19 patients preliminarily suggests an association between IL-6 levels and their QTc maximum measurements over at least 2 days." (PMID 35665254, 2022). "At least in a retrospective evaluation, the FIASMA hydroxyzine was associated with a faster decrease in biological inflammatory markers associated with COVID-19-related mortality, including the neutrophil-to-lymphocyte ratio, the lymphocyte-to-C-reactive protein ratio, and circulating IL-6." (PMID 34608263, 2022). "IL-6 level is a well-known lab parameter associated with worse prognosis in COVID-19." (PMID 34718937, 2022). "In the case of severe COVID-19, insulin resistance may be caused by elevated levels of tumor necrosis factor-alpha (TNFα) and interleukin-6 (IL-6)." (PMID 36548203, 2022). "Moreover, an association between elevated serum ferritin and IL-6, characteristic of the sHLH, and higher mortality rates have been reported in COVID-19 patients." (PMID 35250575, 2022). "To examine whether NP, CRP, and IL-6 were produced through the same signaling pathway in viral infection (COVID-19 patients) and other causes (non-COVID-19 patients), we analyzed their correlations." (PMID 35529699, 2022). "In particular, COVID-19 severity and mortality are strongly associated with IL-6 levels." (PMID 35928820, 2022). "High plasma IL-6 is associated with poor outcome in COVID-19 patients." (PMID 35064792, 2022). "PAI-1 is linked to elevated levels of IL-6 in critically ill COVID-19 patients." (PMID 35784318, 2022). "However, plasma IL-1β, IL-6, IL-8, and chemokine levels were associated with intensive care unit admission and the death of severe COVID-19 patients." (PMID 36430430, 2022). "This study aims to investigate whether TNF-α, IL-6, and vitamin D levels are associated with COVID-19 severity and mortality." (PMID 35215138, 2022). "The high omega-6/omega-3 ratio is extremely proinflammatory, leading to increased expression of CRP, leukotrienes, and ultimately high levels of cytokines including IL-6 of TNF-α that could increase the susceptibility of COVID-19." (PMID 35685606, 2022). "Since the IL6/IL10 ratio has been demonstrated as a sensitive biomarker of COVID-19 outcome, aging PLHTLV-1 might be at increased risk of developing severe or critical COVID-19." (PMID 36482436, 2022). "Furthermore, elevated levels of IL-6 have been associated with a hypercoagulable state in patient with COVID-19." (PMID 36330085, 2022). "COVID-19 may be responsible for the perpetuation of arrhythmias due to an increased catecholaminergic state caused by cytokines such as IL-6, IL-1, and tumor necrosis factor-alpha." (PMID 36614901, 2022). "However, serum IL-6 levels are dramatically elevated and are associated with disease severity and mortality risk in COVID-19." (PMID 35406020, 2022).